UCP1 (uncoupling protein 1)
Diseases named in the same sentence as UCP1 in open-access papers (continued):
Sharing a sentence is not in itself a finding about the gene and the disease.
Obesity (continued). "Hence, UCP1 gene is implicated in the development of these disorders: several studies have reported that polymorphisms -3826A/G, -1766A/G and -112A/C in its promoter region, Ala64Thr in exon 2 and Met299Leu in exon 5 are possibly associated with obesity." (PMID 25871295, 2015). "However, in animal models, obesity could be induced by BAT specific protein uncoupling protein 1 (UCP1) ablation and UCP1 deficiency increases susceptibility to diet-induced obesity with age." (PMID 25894250, 2015). "These SNPs, therefore, may contribute to susceptibility to obesity similar to UCP1-3826G/A." (PMID 25533680, 2014). "The discovery that loss of neuronatin can promote UCP1 induction is a potentially important discovery, and more detailed analysis of neuronatin biochemistry is required before it can be proposed that manipulation of neuronatin represents a point for therapeutic intervention in human obesity." (PMID 23482445, 2013). "We believe that further studies are warranted, with a greater number of subjects, to examine whether other common variants in the FTO and UCP-1 genes could be synergistic in the increased risk for obesity or obesity related phenotypes in the Brazilian and other multiethnic populations." (PMID 23134754, 2012). "The obesity status could have opposing impacts on the relationship between the G/G genotype and low HDL-cholesterolemia, providing insight into the need to consider the obesity levels when studying the association between the UCP-1 gene A-3826G polymorphism and HDL-cholesterol." (PMID 22393344, 2011). "In view of the worldwide epidemic of obesity and associated metabolic disorders it is obviously of importance to identify pathways that can be manipulated genetically or pharmacologically and regulate the induction of UCP1 expression and recruitment of brown-like adipocytes in white adipose tissues." (PMID 20613988, 2010). "This is consistent with our recent report that deletion of Dnmt3b in mature brown adipocytes using Ucp-1 Cre driver ameliorates obesity in female mice." (PMID 41596507, 2026). "Experimental studies in mouse models have demonstrated that RA treatment significantly increases UCP1 expression and suppresses the development of obesity." (PMID 41535542, 2026). "Fucoxanthin, a carotenoid derived from edible marine algae, has been shown to increase UCP1 expression in the BAT of mice genetically predisposed to obesity and type 2 diabetes, thereby partially alleviating obesity symptoms." (PMID 41535542, 2026). "Loss of BMP7 results in brown fat hypoplasia and reduced UCP1 levels, whereas systemic BMP7 administration increases BAT mass and thermogenic capacity, highlighting its therapeutic potential in obesity." (PMID 41596403, 2026). "In vivo optogenetic activation of Ca2+ influx in adipocytes shows that SERCA2-dependent Ca2+ cycling alone can drive UCP1-independent thermogenesis, stimulate glucose oxidation, and protect against diet-induced obesity." (PMID 41596403, 2026). "In murine models of high-fat diet-induced obesity, curcumin supplementation reduced body weight gain and improved cold tolerance by activating UCP1-dependent thermogenesis, consistent with the TGR5–cAMP–PKA–UCP1 axis described in Section 2.1." (PMID 41153686, 2025). "Since differentiation into beige adipocytes leads to energy expenditure via UCP1, food ingredients that promote this process are expected to exhibit anti-obesity effects." (PMID 40220069, 2025). "External factors, such as cold exposure and β3-adrenergic receptor (β3-AR) agonists or peroxisome proliferator-activated receptor gamma (PPARγ) agonists, can induce WAT browning, leading to UCP1-dependent thermogenesis and increased resistance to obesity." (PMID 40369420, 2025). "Evidence has confirmed these mechanisms in vivo using an optogenetic approach to specifically induce UCP1-independent Ca2+ cycling-mediated thermogenesis, which effectively prevented diet-induced obesity by increasing whole-body energy expenditure." (PMID 41009610, 2025).
Obesity (continued). "In contrast, brown adipose tissue (BAT), known for its thermogenic capacity, plays a protective role against obesity by dissipating energy as heat through the action of uncoupling protein 1 (UCP1)." (PMID 40362857, 2025). "Increased activity of PGC‐1α and UCP1 in BAT is associated with improved metabolic rate and reduced fat accumulation, making them important targets for strategies to treat obesity." (PMID 41306340, 2025). "UCP1 enhances energy expenditure by promoting energy dissipation as heat, a process that significantly influences the onset and progression of obesity." (PMID 40867585, 2025). "Stimulating adipose tissue thermogenesis has emerged as a promising strategy for combating obesity, with uncoupling protein 1 (UCP1) playing a central role in this process." (PMID 40051328, 2025). "This possibility is consistent with the observation that Ucp1 knockout mice fed a high-fat diet are resistant to the development of obesity at room temperature, suggesting the presence of a UCP1-independent pathway(s) in thermogenic adipocytes." (PMID 40354343, 2025). "Overall, these results demonstrate that overexpression of MICT1 in Ucp1+ cells protects these mice from diet-induced obesity and insulin resistance via increasing thermogenesis and energy expenditure." (PMID 40355556, 2025). "Obesity induced endogenous UCP1 expression in BAT and WAT in murine models, resulting in increased resting VO2 as compared to that of lean mice." (PMID 39854351, 2025). "IHC analysis confirmed reduced expression of the obesity-related thermogenic marker UCP1 and revealed enlarged lipid droplets in epididymal adipose tissue of HFD mice, indicative of BAT dysfunction, validating successful model establishment." (PMID 41292047, 2025). "Oral administration of SP-8356 protects against high fat diet (HFD) induced-obesity and metabolic diseases in mice accompanied with an increase of UCP1-independent thermogenic gene expression in beige adipocytes." (PMID 39897567, 2025). "ThTr2 inhibition also impairs thermogenic gene activation (e.g., Ucp1, Pgc1α), whereas thiamine enhances their expression, highlighting its key role in thermogenesis and potential for obesity prevention or treatment." (PMID 40292481, 2025). "We further identified the transcription factor ETV4 as a key regulator that binds this enhancer, modulates chromatin accessibility, and drives UCP1 expression, thereby promoting thermogenesis and metabolic protection against obesity and diabetes." (PMID 40324882, 2025). "In this study, we investigate the feasibility of inducing adipose‐specific UCP1 overexpression via modified plasmids as a novel therapeutic approach to address obesity." (PMID 41039748, 2025). "In terms of metabolisms, Mib2 promoted PTEN proteasomal degradation to inhibit FoxO1‐dependent Ucp1 (Uncoupling protein‐1) transcription in brown adipose tissue, which triggers obesity." (PMID 40159625, 2025). "BAT employs mitochondria for ATP synthesis and heat production, with UCP-1 playing a key role by uncoupling respiration from ATP production to generate heat, thus combating obesity." (PMID 40431382, 2025). "This pathway is gaining attention for its therapeutic potential in obesity and metabolic syndrome, especially in individuals with low UCP1 activity." (PMID 41009610, 2025). "Genes implicated in monogenic obesity include POMC, LEP, LEPR, MC3R, and MC4R, while polygenic obesity involves variants in genes such as FTO, UCP1-3, MC4R, ADRB1-3, and SLC6A14." (PMID 41302083, 2025). "A viable approach to enhance energy consumption and combat obesity is to increase the expression of UCP1, thereby promoting adipose thermogenesis." (PMID 41039748, 2025). "In vitro, animal, and human studies have demonstrated that allicin, via the KLF15 signaling cascade, can prevent obesity and related metabolic disorders by increasing the expression of genes specific to brown adipocytes, such as UCP-1." (PMID 40087612, 2025).
Obesity (continued). "This study introduces an innovative strategy to obesity management by leveraging an hADP promoter‐modified plasmid to induce adipose‐specific overexpression of UCP1." (PMID 41039748, 2025). "Generally, increased Ucp-1 expression in adipocytes implies enhanced thermogenic capacity, which is considered an anti-obesity effect." (PMID 41303454, 2025). "In conclusion, Etv4 promotes thermogenesis and enhances systemic metabolism by upregulating Ucp1 expression, thereby providing protection against diet-induced obesity and insulin resistance." (PMID 40324882, 2025). "We aimed to explore the potential of inducing adipose‐specific UCP1 overexpression via modified plasmids as an innovative therapeutic approach for obesity." (PMID 41039748, 2025). "In this study, we revealed that one of the mechanisms by which falcarindiol prevents obesity is by increasing UCP1 expression and mitochondrial respiration in human preadipocyte-derived adipocytes." (PMID 40529474, 2025). "The uncoupling protein 1 (UCP1) gene is known as an obesity-related gene, but the mechanism was unclear because BAT activity was not fully considered or ignored in adult humans at that time." (PMID 39972479, 2025). "In obese conditions, knockout mice of CNOT7, a deadenylase subunit in the complex, were resistant to HFD-induced obesity in mice due to increased energy expenditure driven by up-regulated mRNA level of uncoupling protein 1 (Ucp1) in WATs." (PMID 40424271, 2025). "PPI analysis revealed MTNR1B’s strong association with diabetes, obesity, cancer, and circadian rhythm disorders, collectively known as circadian syndrome, and MTNR1B’s close interaction with thermogenic genes (UCP1, PPARG, and PPARGC1A)." (PMID 40697662, 2025). "It has been suggested that an increased expression of UCP1 in WAT is a metabolic strategy to mitigate the effects of diet-induced obesity, promoting energy expenditure." (PMID 40906363, 2025). "Collectively, this study will reveal the regulatory mechanism that 1-LGPC activates the KEAP1-NRF2 axis to induce UCP1-dependent thermogenesis, offering a lipid-based therapeutic strategy to combat obesity." (PMID 41016603, 2025). "As the key molecule in the autonomic regulation of energy expenditure and adiposity, UCP1 is indispensable in the anti-obesity effect of β3-adrenergic stimulation." (PMID 40411181, 2025). "This study investigated the feasibility of inducing adipose‐selective UCP1 overexpression via modified plasmids as a novel therapeutic strategy for obesity." (PMID 41039748, 2025). "Dietary EAA supplementation has been shown to activate BAT thermogenesis and promote UCP1-dependent mitochondrial uncoupling, thereby conferring protection against obesity and improving insulin sensitivity." (PMID 40983641, 2025). "Allicin has also been identified as a potential preventive agent for obesity and related metabolic diseases by increasing the expression of brown adipocyte-specific genes such as UCP-1 through the KLF15 signaling cascade." (PMID 40087612, 2025). "Since UCP1 is known as a major thermogenic protein in BAT, the relationship between the UCP1 gene and obesity is important in the history of human adaptation and migration to cold regions." (PMID 39972479, 2025). "In contrast, TGR5 activation in the BAT and skeletal muscle can upregulate UCP1, which promotes thermogenesis and energy expenditure, inhibits fat accumulation, and alleviates obesity." (PMID 40867585, 2025). "It is suspected that reduced UCP1 levels play important roles in the development of age-related type 2 diabetes, obesity, and various other diseases and that the protective effect of UCP1 decreases with age." (PMID 40104293, 2025). "Brown adipose tissue (BAT) dissipates energy via UCP1-mediated thermogenesis and is a recognized target for obesity intervention." (PMID 41515244, 2025).
Obesity (continued). "Of note, mKlf9TG mice developed obesity due to decreased UCP1-dependent and UCP1-independent thermogenesis and increased lipid accumulation in adipocytes." (PMID 38331933, 2024). "Another cytokine, IL-27 targets adipocytes directly through activating p38 MAPK-PGC-1α signaling and inducing UCP1 synthesis, which makes it a potential therapeutic target for obesity." (PMID 39582861, 2024). "Formononetin protected mice from diet-induced obesity and facilitated a higher level of energy expenditure through increasing UCP1 following binding to PPARγ." (PMID 39062047, 2024). "BAT has emerged as a potential therapeutic target for obesity due to the presence of uncoupling protein 1 (Ucp1), a thermogenic protein that boosts EE within the body." (PMID 39087083, 2024). "UCP1 is a key protein in brown adipose tissue thermogenesis, so activation of UCP1 can effectively improve obesity and diabetes." (PMID 39850557, 2024). "In this study, we investigate one of these common drugs, N-Acetylcysteine (NAC), on expressions of UCP1 and factors related to thyroid function in adults with obesity." (PMID 38702594, 2024). "Taken together, RvE1 induces the biogenesis of beige fat and improves the metabolic homeostasis in diet-induced obese mice against obesity and insulin resistance in vivo, which is UCP1 dependent." (PMID 38933207, 2024). "Our research provides strong mechanistic evidence that UCP1 is a complex mediator of 18a-induced thermogenesis, which is a critical process in obesity mitigation." (PMID 38927022, 2024). "UCP1 is a hallmark protein in BAT, responsible for diet-induced thermogenesis and playing a role in controlling obesity." (PMID 38784129, 2024). "Several phytochemicals have been demonstrated to date in the literature to support uncoupled protein 1 (UCP1)-related adipose differentiation and thermogenesis capacity, boosting energy expenditure and reducing obesity and its side effects." (PMID 38397458, 2024). "Recent studies have confirmed that WAT browning manifested as UCP1 up-regulation can battle against obesity and hyperlipidemia, making it a promising target for obesity treatment." (PMID 39156823, 2024). "In a model of genetically determined obesity in mice, PPAR alpha activation caused browning through the induction of UCP1 transcription." (PMID 39769065, 2024). "Our data indicate for the first time that TRPV1 activation counters obesity at thermoneutrality permissive for UCP-1 and that the enhanced expression of other thermogenic genes and proteins is not beneficial in the absence of UCP-1." (PMID 39204203, 2024). "Previous studies have demonstrated that the augmentation of UCP-1 through genetic modifications or the administration of pharmacological substances can lead to a decrease in obesity and an enhancement in insulin sensitivity." (PMID 38702594, 2024). "Our earlier data show that dietary CAP significantly antagonizes diet-induced obesity at ambient temperature by activating UCP-1." (PMID 39204203, 2024). "In contrast, BAT is rich in mitochondria, which can divert ATP into heat through uncoupling protein 1 (UCP1) and uncoupling electron transport to maintain temperature balance and fight against obesity." (PMID 39582861, 2024). "To determine the genetic predisposition of this trait, we conducted an association analysis of SNPs of the genes encoding β3-AR (ADRB3) and uncoupling protein 1 (UCP1), which were previously reported to be associated with obesity and related traits." (PMID 38632325, 2024). "As inducers of UCP1 mediated thermogenesis, these compounds have been shown to reduce obesity in high fat diet models of mice, both by activating BAT cells and by inducing the browning of white adipose tissue." (PMID 39568820, 2024). "As expected, based on the large brown-to-white conversion in obesity, the gene analysis showed a decreased UCP-1 and related PGC-1α expression in DIO rats compared to controls, and the tart cherry treatments restored these changes." (PMID 38671836, 2024).
Obesity (continued). "The ability of brown adipocytes to anti-obesity and fulfill their thermogenic function relies on the presence of UCP1 protein." (PMID 39599706, 2024). "These probiotics significantly enhance thermogenesis by increasing UCP1 expression and causing the browning of WAT, which contributes to their anti-obesity effects." (PMID 39125449, 2024). "Here, the authors show that SerpinA1, secreted from the liver, activates mitochondrial UCP1 expression through interaction with EphB2 in adipocytes, contributing to increased energy expenditure, improved glucose metabolism and reduced obesity." (PMID 39532838, 2024). "Brown adipose tissue (BAT) activation is an emerging target for obesity treatments due to its thermogenic properties stemming from its ability to shuttle energy through uncoupling protein 1 (Ucp1)." (PMID 39087083, 2024). "Surprisingly, mice that lack endogenous UCP-1 (UCP-1−/−) were shown to be resistant to diet-induced obesity at ambient temperature but gain weight and become obese when fed a High Fat Diet (HFD) at thermoneutrality." (PMID 39204203, 2024). "UCP-1 serves a critical function in thermogenesis, promoting energy expenditure and preventing obesity." (PMID 38909257, 2024). "Mechanisms dependent on UCP1 play a main role in enhancing obesity, glucose homeostasis, and BAT activity." (PMID 39000187, 2024). "The discovery of non-UCP1-dependent thermogenic mechanisms offers new opportunities for improving obesity and type 2 diabetes." (PMID 38672499, 2024). "While our research did not provide evidence that SPSL activation of UCP1, the reported co-activation of AMPK and UCP1 through the PGC1α pathway suggests further investigation into the role of UCP1 in the anti-obesity effects of SPSL." (PMID 39273687, 2024). "Recently, UCP-1-activated thermogenesis has received much attention among various AT proteins as a potential target for the treatment of metabolic diseases such as obesity." (PMID 38731880, 2024). "In this respect, D-mannose is obviously different from glucose and initiates a complex of ACSS2 and PPARγ to target Ucp1 transcription, thereby improving obesity and its related disorders, such as glucose utilization, insulin sensitivity and liver steatosis." (PMID 38332049, 2024). "UCP1 can uncouple cellular respiration and ATP synthesis, contribute to heat production, and prevent obesity, and an increase in UCP1 content in WAT leads to a significant increase in whole-body energy expenditure." (PMID 38957396, 2024). "Are the attempts to identify pathways for augmenting UCP1 amounts in order to counteract obesity doomed to be in vain?" (PMID 37499977, 2023). "Brown adipose tissue overexpresses UCP‐1 to enhance the uncoupling of mitochondrial respiration, allowing energy to be lost in the form of heat, thereby defending against obesity and related diseases." (PMID 37576042, 2023). "NGS analysis also revealed that UCP1- samples had an under-representation of gene products that have been shown to protect from obesity." (PMID 38069028, 2023). "The HFD downregulates Pgc-1α and Ucp1 mRNA expression in adipose tissue, resulting in decreased energy expenditure and increased diet-induced obesity." (PMID 37114142, 2023). "Our study is important to expand translational research on UCP1 alternative thermogenesis and dietary intervention to treat obesity and T2D." (PMID 37240054, 2023). "Another study evaluating the role of UCP-1 and BAT in an obesity-resistant 129S mice strain found that the ablation of UCP-1 resulted in obesity even in obesity-resistant mice." (PMID 36900198, 2023). "Collectively, these data delineate that the supplementation of EPA entirely mediates the insulin tolerance and obesity-induced inflammation in UCP1 and in a temperature-independent manner." (PMID 37240054, 2023). "Sinapic acid exhibited anti-obesity effects in multiple cell studies by downregulating Pparg, C/ebpa, Srebp-1c, and Fas and upregulating Ucp1, Pgc1a, and Prdm16." (PMID 36839173, 2023).